MALAT1 (metastasis associated lung adenocarcinoma transcript 1)
Diseases named in the same sentence as MALAT1 in open-access papers (continued):
Sharing a sentence is not in itself a finding about the gene and the disease.
gastric cancer (continued). "In our gene expression array to investigate comprehensive mechanism of MALAT1 in gastric cancer, WNT/β-catenin signaling was affected by knock down of MALAT1." (PMID 28077118, 2017). "Our findings highlight the interaction among the lncRNA, MALAT1, RASSF6 and β-catenin during tumorigenesis and progression of gastric cancer." (PMID 28077118, 2017). "Expression of MALAT1 and U6 was determined by SYBR qRT-PCR in nine-teen gastric cancer cell lines and fifty fresh samples of cancer tissue and adjacent tissues." (PMID 28077118, 2017). "We demonstrate that the lncRNA MALAT1 recruits EZH2 to repress PCDH10 and promotes gastric cancer metastasis." (PMID 26871474, 2016). "To determine the biological role of MALAT1 in gastric cancers, we modulated its expression through RNA interference in MKN45 and CTC141 cells, the MALAT1 high-expressed gastric cancer cell lines." (PMID 27486823, 2016). "MALAT1 stabilizes δ-catenin and upregulates HIF-1α expression, thereby enhancing glycolysis and promoting the proliferation, metastasis, and chemoresistance of gastric cancer cells." (PMID 40977700, 2025). "The direct knockdown of MALAT1 in gastric cancer cells also confirmed that it had no impact on δ‐catenin mRNA level but decreased its protein stability." (PMID 38639382, 2024). "CCL21 has been found to be overexpressed in patients with gastric cancer, and further studies have shown that it upregulates the expression of MALAT1, activates the mTOR signaling pathway, and promotes migration, invasion, and epithelial–mesenchymal transition (EMT) of gastric cancer cells." (PMID 39840050, 2024). "Balb/c nude mice were subcutaneously implanted with gastric cancer cells and routinely given intratumoral injections of M2‐EX with or without MALAT1." (PMID 38639382, 2024). "MALAT1 may associate with EZH2, a subunit catalyzing the trimethylation modification in histone 3 Lys27 (H3K27me3), to inhibit the expression of tumor suppressor PCH10 and increase migration and invasion in gastric cancer (GC) cells." (PMID 36452326, 2022). "miR‐30e also interacts with other lncRNAs to negatively regulate cancer progression such as oncogenic lncRNA DLEU2 that promoted esophageal cancer through the miR‐30e/E2F7 axis and MALAT1 which acted as a molecular sponge of miR‐30e to regulate ATG5 expression and autophagy in gastric cancer." (PMID 35612714, 2022). "In gastric carcinoma, there was also a negative correlation of MALAT1 and miR-202, with knockdown of MALAT1 restoring miR-202 expression and reducing transcription factor GLI2 expression, leading to growth inhibition." (PMID 35682549, 2022). "Furthermore, the binding of MALAT1 on miR-30 up-regulates the ATG5 expression, inducing autophagy mechanisms and creating gastric cancer cells resistant to DDP." (PMID 34947835, 2021). "Especially, of the clinical parameters, we noticed that MALAT1 high level was related to early stage in gastric cancer patients but not late stage." (PMID 34308750, 2021). "Aberrant MALAT1 levels have been observed to alter the stability of mRNA splicing proteins SF2/ASF that leads to their dysfunction, an important event needed for the cellular proliferation of gastric cancer." (PMID 29719612, 2018). "Therefore, the results demonstrated that MALAT1 negatively regulated miR-1297 and promote the HMGB2 expression in gastric cancer progression." (PMID 28396617, 2017). "Furthermore, we showed decreased migratory capacity and invasiveness following MALAT1 silencing, and found decreased expression of the mesenchymal markers, N-cadherin and snail, which are major factors that regulate the EMT in gastric cancer cells." (PMID 28077118, 2017). "Plasma MALAT1 levels were significantly higher in gastric cancer patients with distant metastasis than patients without distant metastasis and the healthy controls." (PMID 28396617, 2017). "Additionally, MALAT1 targets the PTX-resistant genes miR-23b-3p and ATG12 in gastric cancer cells." (PMID 38294554, 2024).
gastric cancer (continued). "Additionally, oncogenic lncRNAs MALAT1 and PVT-1 could contribute to 5-FU resistance of gastric cancer by modulating expression of the miR-23b-3p/ATG12 axis and Bcl-2, respectively." (PMID 32192494, 2020). "However, MALAT1 in gastric cancer has not been studied as of yet, and functional and mechanistic studies of MALAT1 are inadequate and unclear." (PMID 28077118, 2017). "We checked the relationship between SRSF1 and MALAT1 in gastric cancer cell lines (data not shown)." (PMID 28077118, 2017). "In all, the current study indicated that MALAT1 up-regulation might be a valuable biomarker for the distant metastasis in gastric cancer patients, and miR-122-IGF-1R signaling might be involved in the MALAT1 dysregulation in gastric cancer." (PMID 27486823, 2016). "However, the functional role of MALAT1 in gastric cancer has not yet been studied." (PMID 28077118, 2017). "We confirmed the interaction between δ‐catenin and β‐TRCP in gastric cancer cells by co‐IP assay and demonstrated that M2‐EX treatment attenuated the interaction between δ‐catenin and β‐TRCP while si‐MALAT1 M2‐EX did not have this effect." (PMID 38639382, 2024).
prostate carcinoma (150 papers, 2013 to 2026). A carcinoma that arises from epithelial cells of the prostate gland. "In prostate cancer, MALAT1 expression showed a strong association with AR positivity (90%), particularly in advanced and castration-resistant tumors." (PMID 40674376, 2025). "Combined biomarker models (e.g., SOX+MALAT1) further improved diagnostic discrimination, with AUCs exceeding 0.90 in colorectal and prostate cancers." (PMID 40674376, 2025). "For example, MALAT1 and lncRNA prostate cancer antigen 3 are being studied as diagnostic markers for prostate cancer." (PMID 38473915, 2024). "Another promising diagnostic biomarker is MALAT-1, known for its high expression in the plasma of patients with prostate cancer." (PMID 38095719, 2024). "Consistent with this, previous studies also demonstrated frequent upregulation of MALAT1 in advanced stage prostate cancer which positively associates with an aggressive clinical phenotype." (PMID 37812088, 2023). "MALAT1-deficient prostate cancer cells upon olaparib treatment show a decrease in the S-phase population compared with the shSCRM control." (PMID 37812088, 2023). "Almost 2-fold higher γH2AX foci per cell were noted in olaparib-treated MALAT1-silenced cells compared with shSCRM control, suggesting that MALAT1 deficiency exacerbates olaparib-induced DNA damage in prostate cancer cells." (PMID 37812088, 2023). "demonstrate that Urinary MALAT‐1 is a clinically valuable biological target for predicting prostate cancer risk." (PMID 35592755, 2022). "MALAT-1 is upregulated in prostate cancer and is associated with the increase in the Gleason score, prostate-specific antigen (PSA), and tumor stage." (PMID 35103065, 2022). "MALAT1 is known to be overexpressed in breast, pancreas, lung, colon and prostate carcinomas, in addition, it is associated with metastasis and poor survival in non-small cell lung cancer patients." (PMID 33803328, 2021). "Compared to PSA screening in prostate cancer, the urinary MALAT1 level is a more accurate diagnostic marker and helps to prevent 30.2–46.5% of unnecessary biopsies without missing any high-grade cancer in populations with PSA 4–10 ng/mL." (PMID 34574033, 2021). "This is the first study to assess MALAT1 polymorphisms and their clinicopathologic impact on Taiwanese men with operatable prostate cancer." (PMID 34574033, 2021). "Although more and more studies have evaluated the regulatory pathway of MALAT1 in prostate cancer, scant data examining the association between MALAT1 SNPs and prostate cancer are available to date." (PMID 34574033, 2021). "In conclusion, MALAT1 SNPs are significantly associated with the susceptibility to both advanced Gleason grade and nodal metastasis in prostate cancer." (PMID 34574033, 2021). "Our study aimed to access the potential roles of MALAT1 polymorphisms in the clinicopathologic features of prostate cancer." (PMID 34574033, 2021). "MALAT1 silencing caused a metabolic rewire in both experimental models adopted, prostate cancer cell lines, and organotypic slice cultures derived from surgical specimens." (PMID 33375130, 2020). "The lncRNA metastasis-associated lung adenocarcinoma transcript 1 (MALAT1) promotes growth and progression in prostate cancer (PCa); however, little is known about its possible impact in PCa metabolism." (PMID 33375130, 2020). "The oncogenic role of MALAT1 has been reported in various cancers, including lung, colon, cervical, ovarian, pancreatic, bladder, and prostate cancers, and has been associated with tumor metastasis." (PMID 32708561, 2020). "Another study in prostate cancer cells revealed opposite functions of metastasis associated lung adenocarcinoma transcript 1 (MALAT1) and HOTAIR in estrogen-associated transcriptional modulation." (PMID 32759784, 2020). "The potentials of lncRNAs for diagnostics are more advanced for cancer, where the lncRNA MALAT1 has been included in a commercially available diagnostic kit for prostate cancer." (PMID 30610612, 2019).
prostate carcinoma (continued). "Based upon our proposed method, prostate cancer was predicted to be associated with H19, MALAT1, CDKN2B-AS1, HOTAIR, PCAT1, SRA1, XIST." (PMID 29671405, 2018). "More importantly, scholars also have found that the expression levels of MALAT-1 can serve as a potential new therapeutic target and diagnostic urinary biomarker for prostate cancer." (PMID 26989678, 2016). "One of the most-studied lncRNAs, MALAT-1 (Metastasis-Associated Lung Adenocarcinoma Transcript 1), is overexpressed during prostate cancer progression." (PMID 27189224, 2016). "Our results demonstrate that urine MALAT-1 is a promising biomarker for predicting prostate cancer risk." (PMID 25526029, 2014). "The metastasis-associated lung adenocarcinoma transcript 1 (MALAT-1) for example, which is expressed in human tissue, becomes up-regulated in various solid tumors, including liver, lung, breast and prostate cancer." (PMID 25119862, 2014). "Similarly, in the event of prostate cancer, MALAT1 has been associated with the promotion of EMT while simultaneously inhibiting apoptosis." (PMID 39323624, 2024). "Collectively, this study provides strong evidence that MALAT1 is indispensable for maintaining genome integrity in advanced-stage prostate cancer, emphasizing a novel therapeutic approach wherein targeting MALAT1 augments sensitivity to PARP inhibition by inducing HR deficiency in prostate cancer." (PMID 37812088, 2023). "Because MALAT1 knockdown contrives HR deficiency in prostate cancer, we speculated that MALAT1-deficient cells would be vulnerable to chemotherapeutic agents that target DNA repair." (PMID 37812088, 2023). "Importantly, we propose a novel therapeutic strategy that emphasizes MALAT1 inhibition, leading to HR dysfunction in both HR-deficient and -proficient prostate cancer, consequently augmenting their susceptibility to PARPi." (PMID 37812088, 2023). "Because both 22RV1 and LNCaP cells harbor inactivating mutations in BRCA1/2 genes, we next examined whether MALAT1 can modulate the HR pathway in HR-proficient prostate cancer cells." (PMID 37812088, 2023). "It is known that the long noncoding RNAs (lncRNA) MALAT1 is associated with tumorigenesis and progression in various cancers; however, its functions and mechanisms in prostate cancer (PCa) initiation and progression are still unknown." (PMID 35557985, 2022). "Hence, further research on larger cohorts and even the international multi-centers to confirm the association between these MALAT1 SNPs and clinicopathological characteristics patients with prostate cancer needs to be conducted." (PMID 34574033, 2021). "However, the associations between MALAT1 SNPs and prostate cancer have barely been investigated to date." (PMID 34574033, 2021). "Because MALAT1 is considered an oncogene in genitourinary cancer, we believed that MALAT1 genotyping variants might enhance its regulatory functions in prostate cancer, being subsequently responsible for cell proliferation and tumor invasion." (PMID 34574033, 2021). "Current evidence elucidates that long noncoding RNA metastasis-associated lung adenocarcinoma transcript 1 (MALAT1) could regulate genetic expression and play a crucial role in both the diagnosis and prognosis of prostate cancer." (PMID 34574033, 2021). "Metastasis-associated lung adenocarcinoma transcript 1 was one of the first identified cancer-associated lncRNA in the lung, bladder, breast, cervical, colon, colorectal, endometrial, esophageal, gastric, lymphoblastoid, ovarian, and prostate cancer." (PMID 33193626, 2020). "Similarly, urinary MALAT1 levels were explored to predict the risk of prostate cancer before biopsy in both discovery and multi-center validation phases." (PMID 28829354, 2017). "The highly specific expression of lncRNAs may also explain why independent reports support the application of cell-free UCA1 and MALAT1 as diagnostic biomarkers for bladder and prostate cancers, respectively." (PMID 28410618, 2017).
prostate carcinoma (continued). "Recently, a series of association studies have proven that Metastasis associated lung adenocarcinoma transcript 1 (MALAT1), an lncRNA used to predict metastasis and survival in patients with early-stage non-small cell lung cancer, is correlated with prostate cancer development and progression." (PMID 28272371, 2017). "MALAT1 (metastasis associated in lung adenocarcinoma transcript 1) has been reported to be a prognostic marker in several cancers, including lung, breast, pancreas, liver, colon, uterus, cervix, and prostate cancers." (PMID 26989421, 2016). "Moreover, several lncRNAs, such as PCA3 and MALAT-1, can be used as diagnostic urinary biomarkers for prostate cancer, thus DANCR expression in the urine of prostate cancer patients should be measured and analyzed in the future." (PMID 27191265, 2016). "MALAT1 is one of the highly cancer-relevant lncRNAs, expression of which is associated with progression of lung, pancreatic, prostate cancer and glioma and therefore, it has been proposed that MALAT1 could be a biomarker of several cancer types." (PMID 26516927, 2015). "MALAT1 overexpression appears to be a promising diagnostic urinary biomarker for prostate cancer." (PMID 26516927, 2015). "In addition, MALAT1 has a possible diagnostic value in prostate cancer." (PMID 37025585, 2023). "In addition to the diagnostic value, recent evidence indicates that MALAT1 could also serve as a therapeutic target in prostate cancer." (PMID 34574033, 2021). "In prostate cancer, MALAT1 facilitates tumor cell proliferation, migration, and invasion by modulating signaling pathways, including the miR‐140/BIRC6 axis, thus contributing to tumor progression." (PMID 41584724, 2026). "HyPR-MS has been instrumental in locating prostate cancer-related complexes, including MALAT1, NEAT1, and NORAD." (PMID 40861865, 2025). "In one study, the authors developed a urinary exosomal lncRNA assay incorporating PCA3 and MALAT1 to diagnose prostate cancer and high-grade prostate cancer." (PMID 39859516, 2025). "MALAT1 showed the highest rate of overexpression, with 80% of colorectal, 70% of breast, and 76% of prostate cancer patients exceeding the expression threshold." (PMID 40674376, 2025). "This study evaluated the expression levels of SOX2, PIWI proteins, and MALAT1 in plasma samples from colorectal, breast, and prostate cancer patients, as well as healthy controls." (PMID 40674376, 2025). "By contrast, in prostate cancer cells, MALAT1 silencing downregulates ME3, PDK1, PDK3, and choline kinase—enzymes critical for OXPHOS." (PMID 41199749, 2025). "In prostate cancer, MALAT1 expression strongly correlated with androgen receptor (AR) positivity (90%, p < 0.001)." (PMID 40674376, 2025). "Quercetin targets MALAT1 and decreases invasion in prostate cancer by upregulating N-cadherin and phosphorylated Akt; downregulating E-cadherin." (PMID 40352931, 2025). "The study investigated the expression levels of SOX2, PIWI proteins, and MALAT1 in plasma samples from patients with colorectal, breast, and prostate cancers, as well as a control group of healthy individuals." (PMID 40674376, 2025). "A study that analyzed MALAT1 expression in prostate cancer patients whose biopsies came back positive and those whose did not found the disease, this lncRNA was shown to be considerably greater in biopsy-positive samples." (PMID 39512820, 2024). "After initial evaluation of ASOs containing mesyl and busyl phosphoramidate groups, we studied Malat1 RNA knockdown (KD) in prostate cancer cells 22Rv1." (PMID 38501046, 2024). "In this study, we combined the PSMA ligand-mediated delivery of ASOs with N-alkanesulfonyl phosphoramidate groups, mesyl and busyl to achieve efficient knockdown of Malat1 lncRNA in prostate cancer cells in vitro." (PMID 38501046, 2024). "In prostate cancer, miR-423-5p was identified as an inhibitor of MALAT1-mediated proliferation and metastasis." (PMID 39323624, 2024).